RGL1 (ral guanine nucleotide dissociation stimulator like 1)
Description:
Probable guanine nucleotide exchange factor.
Synonyms: RGL
Tractability: Small molecule: a structure with a bound ligand is known. Antibody: its Gene Ontology location is reachable by antibodies, with medium confidence.
Gene: Protein-coding gene on chromosome 1 (183,636,085 to 183,928,532, forward strand). Ensembl gene ENSG00000143344.
Subcellular location (Human Protein Atlas): Golgi apparatus; Nucleoplasm; Vesicles
Pathways (Reactome):
Metabolism: PPARA activates gene expression
Signal Transduction: RAF/MAP kinase cascade
Gene Ontology:
Molecular function: protein binding; guanyl-nucleotide exchange factor activity
Biological process: Ras protein signal transduction; small GTPase-mediated signal transduction; signal transduction
Cellular component: cytosol; plasma membrane
Genetic constraint (gnomAD): Loss-of-function variants: 15 observed, 72.08 expected, observed/expected ratio (o/e) 0.21, 90% interval 0.14 to 0.32. The upper end of that interval is the gene's LOEUF score, 0.32, which puts it in group 1 of 6, group 1 being the genes least tolerant of losing a copy. Missense variants: 633 observed, 859.65 expected, observed/expected ratio (o/e) 0.74, 90% interval 0.69 to 0.79. Synonymous variants: 285 observed, 318.67 expected, observed/expected ratio (o/e) 0.89, 90% interval 0.81 to 0.99.
Homologues: Orthologues: chimpanzee RGL1 (99% identical), macaque RGL1 (98% identical), dog RGL1 (96% identical), pig RGL1 (95% identical), mouse Rgl1 (95% identical), guinea pig RGL1 (95% identical), rat Ralgdsl1 (93% identical), zebrafish rgl1 (67% identical). Paralogues in human: RALGDS (49% identical), RGL3 (37% identical), RGL2 (32% identical), RAPGEF2 (19% identical), RGL4 (18% identical), RAPGEF6 (17% identical), RAPGEF1 (15% identical), SOS1 (15% identical), SOS2 (15% identical), RALGPS2 (14% identical), RALGPS1 (14% identical), RAPGEF3 (13% identical), and 12 more.
Diseases named in the same sentence as RGL1 in open-access papers:
RGL1 is named in the same sentence as 15 diseases in open-access papers, as found by Europe PMC text mining. Sharing a sentence is not in itself a finding about the gene and the disease. The quoted sentences say what the papers report.
lung carcinoma (2 papers, 2018 to 2019). "For SNP pair rs74826777:rs1474960, from RGL1:RAD51B gene pair, individuals with genotype 1/0 had a lung cancer risk effect with OR 1.31 and p value 0.01 whereas individuals with genotype 1/1 had a reduced effect with OR 0.51 and p value 6.46x10-7." (PMID 30956756, 2019). "We successfully identified epistasis in RGL1:RAD51B in ALL and NSCLC lung cancer, SYNE1:RNF43 in ADE and FHIT:TSPAN8 in SQC risk development." (PMID 30956756, 2019). "Interestingly, all the three significant epistasis—-RGL1:RAD51B in ALL and NSCLC lung cancer, SYNE1:RNF43 in ADE and FHIT:TSPAN8 in SQC risk development—-were displayed as interaction between networks." (PMID 30956756, 2019). "In NSCLC lung cancer cohort, IPA created two top gene networks with RAD51B in one network and RGL1 in the other." (PMID 30956756, 2019). "For the genetic interaction between RGL1 and RAD51B gene, we identified 7 and 3 SNP pairs with joint p value < 1.95x10-10 from the ALL lung cancer and NSCLC cohort, respectively." (PMID 30956756, 2019). "Take the rs74826777:rs17835244 pair from RGL1:RAD51B gene pair as an example, these two SNPs had p value of 0.16 and 0.02 in single-locus association analysis in ALL lung cancer cohort, respectively, indicating no significant main effect in lung cancer development." (PMID 30956756, 2019).
colorectal cancer (1 paper, 2021). A primary or metastatic malignant neoplasm that affects the colon or rectum. "We first analyzed the transcriptional profiling of RGL subtypes RGL1, RGL2, RGL3, and RGL4 in The Cancer Genome Atlas (TCGA) colorectal cancer (CRC) database." (PMID 33917100, 2021).
hepatitis B (1 paper, 2024). "Furthermore, we explored public GWAS databases containing data on HBV recurrence after LT in HBsAg-positive hepatitis B patients, recruited in other ethnic populations, to validate the SNP markers located on RGL1, CDCA7L, and AQP9 genes identified in the entire cohort." (PMID 39796114, 2024).
steatosis (1 paper, 2022). Increased lipid within the cytoplasm of cells. "Only rs2491441 (RGL1) was significantly associated with both steatosis and advanced fibrosis and both associations were very strong [AORs = 8.62 (1.11–66.86), p = 0.039 and 4.06 (1.04–15.78), p = 0.043]." (PMID 36386790, 2022).
cancer (3 papers, 2018 to 2023). A tumor composed of atypical neoplastic, often pleomorphic cells that invade other tissues. "As RGL1 and WNT10A are widely expressed in both normal and cancer tissues, determining the immunogenic epitopes that autoantibodies target could lend insight into the interactions of the immune system and tumorigenesis." (PMID 37444527, 2023).
RGL1 also shares sentences with these, for which no sentence is quoted: adenocarcinoma (2 papers); tumor (2); atherosclerosis (1); bacterial infection (1); breast carcinoma (1); diabetes (1); liver fibrosis (1); neurological disorders (1); non-small cell lung carcinoma (1); squamous cell carcinoma (1).